TLR4 (toll like receptor 4)
Diseases named in the same sentence as TLR4 in open-access papers (continued):
Sharing a sentence is not in itself a finding about the gene and the disease.
Obesity (continued). "FATP4 and TLR4 might be employed as possible medications for obesity and other obesity-related conditions, such as steatosis of the liver." (PMID 36360622, 2022). "The activation of TLR-4 and its coreceptor CD14 are associated with obesity and insulin resistance in mice and may represent one of the key elements connecting inflammation to increased susceptibility to weight gain and impaired glucose homeostasis." (PMID 35335996, 2022). "However, the involvement of TLR4 signaling in HSC regulation under conditions of obesity is unclear." (PMID 35163498, 2022). "The TLR4/NF-κB pathway may also have a significant impact on acupuncture treatment of obesity through IL-6." (PMID 36105933, 2022). "Our findings demonstrate MEP supplementation attenuates obesity parameters and reduces inflammation in the colon via regulation of Toll-like receptor 4 (TLR4), nitric oxide synthase (iNOS), cyclooxygenase-2 (COX-2), and inactivation of nuclear factor kappa B (NF-κB)." (PMID 36056976, 2022). "Since CD44 was able to reduce adiposity in C3H/HeJ mice, we can infer that the mechanism underlying obesity resistance in CD44-deficient mice is not driven solely by the inflammatory response of the TLR4 pathway." (PMID 35410390, 2022). "We found that the obese state upregulated ERα expression in a murine model of obesity-associated BC, and demonstrated contribution of Mφ, adversely-activated by obesogenic substances (e.g., SFA) through TLR4-dependent mechanism, to ERα upregulation in mouse/human BC cells." (PMID 36139419, 2022). "Quinoa showed distinct downregulation on TLR4 in the colon and liver as well as ER stress, which suggested quinoa could ameliorate inflammatory status in obesity." (PMID 35583337, 2022). "On the other hand, our observations in TLR4−/− mice do correlate with previously published results showing that loss of function of TLR4 partly prevented diet-induced insulin resistance in mice and selectively protected against obesity." (PMID 36555322, 2022). "High n-6 PUFA intake has been reported to upregulate TLR4 expression, and a high dietary n-3/n-6 PUFA ratio has been shown to ameliorate obesity-associated inflammation and insulin resistance by inhibiting TLR4 activation in rats, which also reflects TLR4 upregulation by n-6 PUFA." (PMID 35571243, 2022). "It has been shown that free fatty acids (FFA), which are elevated in obesity, may promote TLR4 signaling, which in turn contributes to obesity-related insulin resistance." (PMID 35625904, 2022). "Mohamad reported that administrate with withaferin A (1.25 mg/kg/d) for 12 weeks protected against high-fat diet induced obesity through reducing hepatic mRNA expressions of TLR4, NF-κB, TNF-α), chemokine (C-C motif) ligand-receptor, and cyclooxygenase 2 (COX2)." (PMID 35769384, 2022). "Also, some authors have suggested miR-194 as a regulator of the TLR4 signaling pathway in obesity-driven inflammatory response and necrotizing enterocolitis." (PMID 35598011, 2022). "MiR883b-5p, which is upregulated by APN and lowered in obesity, showed an inhibitory effect on lipopolysaccharide (LPS)-binding protein and Toll-like receptor 4 (TLR4) signaling, thus acting as an important mediator of the anti-inflammatory activity of this adipokine." (PMID 35409299, 2022). "Moreover, several other obesity-related inflammatory factors, including IL-17, leptin, adiponectin, NLRP3 inflammasome, and TLR-4 have been implicated in the pathogenesis of lung disease." (PMID 35360873, 2022). "The results showed that the anti-inflammatory and anti-oxidation effects of Ka were closely related to the TLR4/IκBα/NF-κB signaling pathway, which could effectively improve obesity and glycolipid metabolism disorders in obesity." (PMID 34094031, 2021). "It has been hypothesized that FFA can bind and stimulate TLR4; thus, the elevated plasma level of FFA observed in obesity could activate TLR4." (PMID 33809891, 2021).
Obesity (continued). "On this aspect, some authors have reported that TLR4 is involved in obesity and liver damage." (PMID 34445644, 2021). "To investigate whether CGA improves IR and obesity by regulating the TLR-4 pathway, we assayed TLR-4 expression in liver and epididymal fat." (PMID 34975748, 2021). "When bound to its receptor Toll-Like Receptor 4, LPS stimulates whole-body and tissue specific metabolic perturbations by initiating a signaling cascade that results in inflammatory pathways and further promotes obesity and insulin resistance." (PMID 34432833, 2021). "Additionally, the PRSS8 levels are diminished by the endoplasmic reticulum stress, a characteristic condition with high-fat diet or obesity, leading to insulin resistance when TLR4 was less inactivated." (PMID 34361079, 2021). "TLR4 plays critical roles in innate immunity through inducing inflammatory cytokine, and abnormal activation of TLR4 could induce obesity-induced inflammation." (PMID 34203004, 2021). "Furthermore, another pathway involved in obesity inflammation is those triggered by toll-like receptor 4 (TLR4)." (PMID 33923599, 2021). "The miRNA miR-223 has been implicated in IR and obesity by modulating STAT signaling pathways, the toll-like receptor 4 (TLR4), and the F-box/WD repeat-containing protein 7 (FBXW7), a negative regulator of adipogenesis and a tumor suppressor in many cancer types." (PMID 34681797, 2021). "A recent study unveiled that toll-like receptors TLR2 and TLR4 in islets may integrate inflammatory signals in diet-induced obesity to attenuate adaptive changes that govern β-cell replication." (PMID 33817571, 2021). "On the one hand, excess lipids in adipose tissue due to obesity stimulate the local production of fetuin-A via the TLR4 and Nf-κB signaling cascade, creating a local microenvironment that stimulates M1 polarization and the release of pro-inflammatory cytokines along the same signaling axis." (PMID 33483479, 2021). "Although the TLR4 signalling pathway is also involved in the phagocytic response, it is acknowledged as one of the main triggers of the obesity-induced inflammatory response, in accordance with the elevated percentage of monocytes from obese animals expressing TLR4 observed in the present study." (PMID 32429330, 2020). "Although we are not aware of any studies which directly demonstrated elevated LPS levels in the pancreas during obesity-associated PDAC development, other studies have suggested the importance of LPS for β-cell function in obese rats with deficiency in TLR4, the receptor for LPS." (PMID 32709161, 2020). "Moreover, saturated fatty acids that accrue in obesity induce the activation of toll-like receptors-4 (TLR4), resulting in increased inflammation and augmented mRNA expression of various enzymes involved in de novo ceramide biosynthesis." (PMID 32636806, 2020). "TLR4 signaling plays crucial roles in pathogenesis of obesity and metabolic disorders." (PMID 32378734, 2020). "Moreover, TLRs, especially TLR2 and TLR4, induce insulin resistance, which is crucial in the pathogenesis of obesity." (PMID 32429330, 2020). "Previous studies demonstrated that TLR4 activation could active CaMKII cascades under myocardial stress and TLR4 is the upstream regulator of CaMKII, CaMKII exert a vital effect in obesity-induced electrical remodeling." (PMID 32733242, 2020). "As a classical acute-phase protein produced by hepatocytes, SAA mediated infection, injury, and inflammation response and could regulate toll-like receptor 4 (TLR4), which participated in obesity-induced insulin resistance." (PMID 33603714, 2020). "The upregulation of TLR4 protein plus the polymorphism of TLR4D299G/T399I may highlight the higher risk and the impact of TLR4 in obesity-associated inflammation with IR that precede diabetic and cardiovascular events." (PMID 32708841, 2020).
Obesity (continued). "When bound to its receptor Toll-Like Receptor 4, LPS stimulates whole-body and tissue specific metabolic perturbations by initiating a signaling cascade that results in pro-and anti-inflammatory pathways and initiates obesity and insulin resistance." (PMID 32290353, 2020). "To determine the potential role of TLR4 in inhibiting proper adipogenesis during obesity, we stimulated adipocytes derived from WT and Tlr4−/- male mice EMSCs with LPS or palmitate during their differentiation in vitro and assessed adipogenic and inflammatory markers." (PMID 32403975, 2020). "Further, TLR4 has been suggested to play a role in beta cell failure during diet-induced obesity in mice, as HFD-fed TLR4 knock out mice exhibit preserved insulin secretory function, lower inflammatory markers and no macrophage infiltration in pancreatic islets." (PMID 33178196, 2020). "Furthermore, our former work demonstrated that TLR4/MyD88/CaMKII signaling pathway contributed to obesity-induced ventricular electrical remodeling." (PMID 32733242, 2020). "Interestingly, although the phenotypes of TLR4-deficiency and IRF5-deficiency are near identical under diet-induced obesity, the TLR4-IRF5 axis remains to be experimentally confirmed in the pathogenesis of T2D and its complications." (PMID 32140136, 2020). "Additionally, HFD-induced changes to the gut microbiota exacerbates inflammation and obesity via TLR4 induction and NF-κB." (PMID 33603741, 2020). "TLR4 is a molecular link among the immune system, inflammation, IR and obesity." (PMID 32708841, 2020). "Dietary saturated fatty acids (SFAs), whose intake is strongly associated with an increased risk of obesity, have been identified as potent priming agents of the NLRP3 inflammasome via TLR4 in DCs, resulting in elevated expression of pro-IL-1β, caspase-1, TLR4 and NLRP3." (PMID 32545355, 2020). "The levels of free fatty acid (FFA), and lipopolysaccharide (LPS) released by gut bacteria increase during obesity which triggers activation of the (i) Toll-like receptor 4 (TLR4) pathway, (ii) adipose tissue macrophages as well as (iii) nuclear factor-kappa β (NF-κβ) pathway." (PMID 33195370, 2020). "A previous study reported that innate immunity modulated by TLR4 and the intestinal microbiota could be the missing connection in the MeS pathogenesis which link obesity to diabetes mellitus." (PMID 32708841, 2020). "In contrast, activation of the TLR4/MyD88 signaling pathway enhances CaMK II activity, thereby facilitating LV remodeling in the setting of chronic pressure overload or obesity to some extent, illustrated that TLR4/MyD88/CaMK II pathway mediated inflammation involved hypertrophic remodeling." (PMID 33324685, 2020). "The mechanisms controlling TLR-4 activation in obesity have been controversial." (PMID 33072120, 2020). "M1-type macrophages highly express TLR4 and infiltrate into the target metabolic organs of obesity." (PMID 31582899, 2019). "The TLR4 signaling pathways are the main triggers of the obesity-induced inflammatory response." (PMID 31010163, 2019). "TLR4 is a major molecular target for SFAs in the hypothalamus that stimulates intracellular signaling pathways to induce an inflammatory response and contributes to obesity." (PMID 31731503, 2019). "Furthermore, brain specific deletion of MyD88 (myeloid differentiation factor), a downstream mediator of TLR4 signaling, in mice also prevent HFD-induced obesity and associated leptin and insulin resistance." (PMID 30906281, 2019). "The inflammatory process that occurs in obese people differs from the classical inflammatory response; the toll-like receptor 4 signaling pathway, which is activated by saturated fatty acids, has been acknowledged as one of the main triggers of the obesity-induced inflammation." (PMID 30999680, 2019). "Additionally, other groups have provided evidence for the involvement of TLR4 in the pathogenesis of obesity and insulin resistance." (PMID 31197747, 2019).
Obesity (continued). "Thus, inhibition of TLR4 signaling has been shown as an attractive therapeutic strategy for treatment of obesity-induced insulin resistance and adipocytes mediated chronic inflammation." (PMID 30863401, 2019). "Nevertheless, some reports do not support such a role of TLR4 in obesity and associated metabolic dysfunctions." (PMID 30906281, 2019). "In addition, clinical evidence showed substantial increased expression of TLR-4, IL-6, and IL-8 in the placenta of obese women, and TLR-4 ablation in the ARC nucleus of murine models prevents obesity." (PMID 31159189, 2019). "Ceramides play a vital role in TLR4-dependent insulin resistance in obesity." (PMID 31447702, 2019). "Insulin has a suppressive effect on the expression of TLR4 and on the activity of the PU.1 transcription factor; however, the suppressive effect of the hormone would be expected to be reduced due to the insulin-action resistance related to obesity." (PMID 29601492, 2018). "However, the effects of Tlr4 knock-outs on HFD-induced obesity reported in the literature are contradictory." (PMID 30353127, 2018). "The major differences in gut microbial composition of the Tlr4−/− and Cd14−/− mice did not lead to differences in susceptibility to obesity compared to the Wild-Type mice." (PMID 30353127, 2018). "In conclusion these results show susceptibility to a high fat diet is independent of TLR4 signalling and do not support the concept of metabolic endotoxemia as a determinant of obesity." (PMID 30353127, 2018). "We show that BM malfunction arises early in obesity and depends on precursor-intrinsic TLR4." (PMID 29453396, 2018). "A recent study on bone marrow lympho-myeloid malfunction in obesity questioned the role of fetuin-A as a physical adapter between TLR4 and dietary saturated fats and earlier studies showed that LPS-free fetuin-A is anti-inflammatory and protects against vascular smooth muscle calcification." (PMID 30233585, 2018). "Additionally, these findings point to TLR4 as a therapeutic target for obesity, which has important health implications for a range of systemic and neural disorders including type 2 diabetes, cardiovascular disease, and dementia." (PMID 30396359, 2018). "In contrast to our findings, however, many of these studies show that obesity-associated dysregulation of insulin and glucose signaling was improved in the absence of TLR4 signaling." (PMID 30396359, 2018). "TLR2 and TLR4 have been widely studied and have both been shown to play a role in the pathogenesis of lipid disorders like atherosclerotic cardiovascular disease, insulin resistance, and obesity." (PMID 30666212, 2018). "Given this intersection of ageing, inflammation, TLR4 and diabetes, we hypothesized that ageing may have a potentiating effect upon obesity-induced tissue inflammation through TLR4, which would lead to an acceleration of the diabetes phenotype." (PMID 29426925, 2018). "We conclude that BM-intrinsic TLR4 is required for lympho-myeloid malfunction in obesity." (PMID 29453396, 2018). "Indeed, obesity-dependent TLR4 signals were shown to directly activate macrophage production of pro-inflammatory cytokines that contribute to inflammation and insulin resistance." (PMID 29453396, 2018). "Therefore, in this study the aim was to compare the effects of either Tlr4 or Cd14 gene knock-outs in mice on the same genetic background for diet-induced obesity in response to a HFD." (PMID 30353127, 2018). "We conclude that cell-intrinsic TLR4 is required for BM malfunction in obesity." (PMID 29453396, 2018). "It is well-established that obesity is a low grade inflammation and saturated fatty acid palmitate could act as a ligand for toll-like receptor 4 (TLR4) to induce inflammation in adipocytes." (PMID 28261091, 2017). "Then, we further investigated whether resveratrol affected obesity-related OA by reducing systematic inflammation and/or inhibiting TLR4 signaling pathway in cartilage." (PMID 28250578, 2017).
Obesity (continued). "Whether hypothalamic arcuate nucleus (ARC)-restricted TLR4 knockdown improves obesity-related metabolic disorders remains unexplored." (PMID 28785099, 2017). "Thus, down-regulation of TLR4 expression or blockade of TLR4 signaling pathway in the hypothalamus is sufficient to ameliorate obesity-related liver diseases and adipocyte hypertrophy." (PMID 28785099, 2017). "In the present investigation, we found that GSTO1-1 deficient mice consuming a high fat diet present a similar phenotype to that of TLR4 and MyD88 deficient mice and do not exhibit marked obesity and insulin resistance." (PMID 29259211, 2017). "Obesity may cause chronic, low-grade systemic inflammation through increased levels of TNF-α, IL-6, leptin, free fatty acids, and TLR4 and decreased adiponectin levels." (PMID 29049401, 2017). "TLR4 and MyD88 play prominent roles in signaling that supports low level inflammation in obesity." (PMID 29259211, 2017). "Additional to organelle stress, Toll-Like receptors, including TLR2 and TLR4 have received attention for their roles in the development of obesity and insulin resistance, although the mechanisms by which they contribute still remain unclear." (PMID 28883915, 2017). "In summary, this study has confirmed the detrimental effect of EGFR activation in the pathogenesis of obesity-induced cardiac inflammatory injuries in experimental mice, and has demonstrated the TLR4/c-Src-mediated mechanisms for PA-induced EGFR signaling pathway activation in H9c2 cells." (PMID 27087279, 2016). "Furthermore, our data are in agreement with those showing that TLR-4 knockout mice are protected against high-fat diet-induced obesity, inflammation, and insulin resistance and exhibited reduced insulin-mediated changes in systemic glucose metabolism." (PMID 27881903, 2016). "This could suggest that in Chinese middle-aged men, TLR4-mediated inflammatory signaling may be more related to obesity when compared to TLR2." (PMID 27481183, 2016). "HF diet also induced obesity and may have triggered intestinal inflammation since fecal levels of LPS and TLR4 expression tended to be increased in the animals fed with this diet." (PMID 27134637, 2016). "To this end using a model of diet-induced obesity, where mice are exposed to high-fat diet for several months, we assessed visceral sensitivity and alterations in expression of TLR4 and microglia within the CNS, in the PFC and the hippocampus, two areas implicated in pain processing." (PMID 27159520, 2016). "Our data reveal a role for TLR4 in visceral pain modulation in a model of diet-induced obesity, and point to TLR4 as a potential therapeutic target for the development of drugs to treat visceral hypersensitivity present in pathologies associated to fat diet consumption." (PMID 27159520, 2016). "In the present study, we investigated whether there is a functional link between the role of TLR4 in diet-induced obesity and the reported modulatory function of TLR4 in visceral hypersensitivity." (PMID 27159520, 2016). "Systolic blood pressure increase with obesity was blunted in cases with TLR4 SNP rs4986790." (PMID 26435700, 2015). "Interestingly, a significant factor in the relationship between obesity and inflammation is the infiuence of the TLR4 signaling pathway." (PMID 25923657, 2015). "This strengthens the role of TLR4 in IH-induced inflammation, as well as the pathophysiological similarities with obesity, that is, a normal amount of fat under hypoxia behaving like excess fat in obesity." (PMID 25873766, 2015). "Another source of TLR4 activation is the translocation of bacterial endotoxin [lipopolysaccharide (LPS)] from the gut into the blood stream, the so-called metabolic endotoxemia that occurs with diet-induced obesity." (PMID 26435700, 2015).